PAFAH1B1 (platelet activating factor acetylhydrolase 1b regulatory subunit 1)
Diseases named in the same sentence as PAFAH1B1 in open-access papers (continued):
Sharing a sentence is not in itself a finding about the gene and the disease.
Lissencephaly (continued). "A different patient involved in this case study had a partial deletion of PAFAH1B1 resulting in isolated grade 3 lissencephaly and epilepsy." (PMID 29628935, 2018). "Mice with heterozygous deletion of Pafah1b1 exhibit many phenotypes of human lissencephaly, including defects in neuronal migration, disorganization of cortical and hippocampal lamination, deficits in spatial learning and epilepsy." (PMID 28811646, 2017). "The identification of a small 115-kb microdeletion disrupting PAFAH1B1(LIS1) gene is consistent with the clinical presentations of lissencephaly and IS." (PMID 24885232, 2014). "Decreased expression of Dcx and/or Pafah1b1 contributes to Lissencephaly that is characterized by “smooth brain appearance”." (PMID 23776576, 2013). "It is known that heterozygous 17p13.3 deletions, including PAFAH1B1 (MIM 601545) and YWHAE (MIM 605066) genes, cause two clinically distinct disorders: LSI (isolated lissencephaly) or MDS (Miller-Dieker syndrome), depending on the size of the deletion." (PMID 23035971, 2012). "The lissencephaly phenotype of Pafah1b1 heterozygous mutants sparked interest in exploring the relationship between the Pafah1b complex and the Reelin pathway, including the VLDLR and ApoER2 receptors." (PMID 21554715, 2011). "By contrast, MDS consists of severe classical lissencephaly associated with other symptoms, such as facial anomalies, and MDS patients have larger heterozygous deletions that include the PAFAH1B1 (LIS1) and YWHAE (14-3-3ε) genes, compared with patients with ILS." (PMID 35053800, 2021). "Consequently, Pafah1b1 haploinsufficiency results in classical, or Type I, lissencephaly (‘smooth brain’), a rare neurodevelopmental disorder characterized in humans by brain malformation, intellectual disability, motor impairment, and drug-resistant epilepsy." (PMID 33150866, 2020). "Creation of a Crk/Pafah1b1 double knockout could help determine if deletion of these genes contributes to the lissencephaly phenotype in a dose-dependent manner, as this seems to be the case when CRK and YWHAE are deleted together in humans." (PMID 29628935, 2018). "Deletions involving several of the highly differentiated genes in this region have been suggested to contribute to MDS, including PAFAH1B1 (the primary lissencephaly-related gene, also known as LIS1, CFA9:46,647,994–46,727,422), MNT (CFA9:46,466,709–46,482,614) and SMG6 (CFA9:46,161,531–46,405,748)." (PMID 28806925, 2017). "The CNV loss at 17p13.3 contains PAFAH1B1 (LIS1), a causative gene for lissencephaly." (PMID 24885232, 2014). "LIS1 (PAFAH1B1) mutation can impair neuronal migration, causing lissencephaly in humans." (PMID 23483716, 2013). "Our novel findings of LIS1 functions in cytokinesis may explain the mechanism of the recent studies with induced pluripotent stem cells (iPSCs) of Miller Dieker syndrome, a severe form of lissencephaly with haploinsufficiency of PAFAH1B1 as well as about 20 other genes." (PMID 32159512, 2020). "Compared to LIS1/PAFAH1B1, DCX-related lissencephaly patients showed significantly better neurodevelopmental outcome in reaching more advanced milestones such as walking unassisted (z=-2.23, p = 0.026) and speaking sentences (z=-2.53, p = 0.011)." (PMID 42177523, 2026). "PAFAH1B1 gene, coding for LIS1 protein, is a responsible gene for lissencephaly and MDS and regulates neuronal migration by controlling microtubules (MTs) and cargo transport along MTs via dynein." (PMID 35053800, 2021). "Current animal models for lissencephaly and MDS are Pafah1b1, Ywhae, and Crk single-KO models and the Pafah1b1/Ywhae double-KO model." (PMID 35053800, 2021). "It was originally identified as the central nervous system (CNS) specific partner of LIS1 (known as PAFAH1B1), whose haploinsufficiency results in lissencephaly (smooth brain)." (PMID 25245017, 2014). "As with lissencephaly, YWHAE, CRK, and PAFAH1B1 have complicated roles in epilepsy." (PMID 29628935, 2018).
epilepsy (19 papers, 2008 to 2025). A brain disorder characterized by episodes of abnormally increased neuronal discharge resulting in transient episodes of sensory or motor neurological dysfunction, or psychic dysfunction. "Patients with either ILS or MDS have a heterozygous loss of the PAFAH1B1 gene in the 17p13.3 locus and display combinatorial defects, including neuronal migration defects, epilepsy, and craniofacial defects." (PMID 35053800, 2021). "Our findings that GABA neuron migration and function is altered by Pafah1b1 haploinsufficiency is critically important to our understanding of malformation-associated epilepsies and for identifying new therapies." (PMID 28811646, 2017). "Of the 30 protein coding genes with identified coding sequence or expression differences, ten had a prior association with seizure or epilepsy based on literature and database searches, including Aspa, Hic1, Nlrp1a, Nlrp1b, Pafah1b1, Smg6, Trpv1, Trpv3, Ywhae and 6330403K07Rik." (PMID 35606653, 2022). "The third epilepsy-associated variant in PNES was a PAFAH1B1 gene disrupting 17p13.3 deletion." (PMID 32938993, 2020). "Patients with chromosome 17p13.3 deletions involving CRK and YWHAE but not PAFAH1B1 were reported, and they showed generalized epilepsy, growth retardation, and macrocephaly, implicating Crk deficiency in epilepsy." (PMID 35053800, 2021). "Pafah1b1 mutant mice develop handling-induced seizures, spontaneous epilepsy and early death." (PMID 28811646, 2017). "Other systems disrupted by Pafah1b1+/− (e.g., cytoskeleton) or non-neuronal cell types implicated in epilepsy (e.g., astrocytes) are also likely involved." (PMID 28811646, 2017). "Thus, YWHAE, CRK, and PAFAH1B1 are critical genes involved in epilepsy." (PMID 29628935, 2018). "Among pathogenic variants, only PAFAH1B1 was not previously reported to be related to neurodevelopmental disorder including ASD, ID, and epilepsy." (PMID 32477112, 2020). "Two patients with deletions of YWHAE and CRK, but not PAFAH1B1, were described as having macrocephaly, epilepsy, and non-specific changes in white matter, among other clinical features." (PMID 29628935, 2018).
Miller-Dieker syndrome (19 papers, 2008 to 2024). "The Miller-Dieker syndrome (MDS) is localized in the more distal region 17p13.3 containing the PAFAH1B1 (encoding LIS1) and YWHAE genes." (PMID 23035971, 2012). "Diseases associated with PAFAH1B1 include Lissencephaly 1 and Miller-Dieker Lissencephaly Syndrome." (PMID 34348663, 2021). "These included well characterised syndrome regions eg Di-George (OMIM 188400), Williams (OMIM 194050) and Miller-Dieker syndrome (OMIM 247200) regions as well as smaller imbalances with imbalance of critical genes eg PAFAH1B1 (OMIM 601545) and HCCS (OMIM 300056) genes." (PMID 28396697, 2017).
neuronal migration disorder (15 papers, 2013 to 2025). "miR-200a-3p targets Pafah1b1 (platelet activating factor acetylhydrolase 1b regulatory subunit 1), which causes type I lissencephaly, a neuronal migration disorder, upon haploinsufficiency." (PMID 35216219, 2022). "LIS1 (Lissencephaly 1) (officially known as PAFAH1B1) was the first gene to be identified as involved in a neuronal migration disorder (review Reiner, 2013)." (PMID 31474834, 2019).
developmental delay (14 papers, 2011 to 2025). "Notable genes such as PAFAH1B1, involved in neuronal migration, are associated with cortical malformations like schizencephaly and developmental delays." (PMID 40243517, 2025). "The PAFAH1B1 gene is associated with developmental delay, microcephaly, small body size, and other brain malformations." (PMID 32951212, 2021). "Isolated duplications of PAFAH1B1 have been associated with mild developmental delay and hypotonia, while isolated duplications of YWHAE have been associated with autism." (PMID 23035971, 2012). "Class II microduplications always involve PAFAH1B1 and may extend to CRK and YWHAE and have been associated to hypotonia, mild developmental, and psychomotor delay." (PMID 23035971, 2012).
Lissencephaly-1 (14 papers, 2007 to 2025). "LIS1 (PAFAH1B1) plays a major role in the developing cerebral cortex, and haploinsufficient mutations cause human lissencephaly type 1." (PMID 35309904, 2022). "PAFAH1B1 (Platelet-Activating Factor Acetylhydrolase 1b Regulatory Subunit 1) encodes the protein LIS1, short for Lissencephaly-1, reflecting the phenotype that occurs in humans and mice with its loss of function." (PMID 40378956, 2025). "An illustrative example of this class of SV was a 100kGP participant with lissencephaly 1 (MIM: 607432) harboring a 256-kb inversion disrupting PAFAH1B1 (MIM: 601545; Family 13)." (PMID 38776926, 2024). "The gene in the highest level node of the hierarchical similarity graph was Pafah1b1, platelet-activating factor acetyl-hydrolase, isoform 1b, subunit 1, also known as Lis-1, for lissencephaly, type 1." (PMID 26834590, 2016). "Among the most prominently induced are Pafah1b1 (platelet activating factor acetyl hydrolase 1B)/Lis1 (lissencephaly type 1), Peripherin and Annexin A2, and siRNA knockdown of each of these proteins significantly reduced the numbers of PRV capsids undergoing retrograde traffic along the axon." (PMID 31861082, 2019).
microcephaly (13 papers, 2008 to 2026). A congenital or acquired developmental disorder in which the circumference of the head is smaller than normal for the person's age and sex. "Due to the haploinsufficiency of PAFAH1B1 and YWHAE in MDS, neuronal migration defects contribute to the “smaller head” phenotype (i.e., microcephaly) observed in these organoids, primarily through the disruption in the cortical niche architecture." (PMID 40806509, 2025).
Intellectual disability (8 papers, 2018 to 2025). "Duplications on the 17p13.3 chromosomal region, impacting genes such as YWHAE, CRK, and PAFAH1B1, are established risk factors for various neuropsychiatric conditions, including intellectual disability, autism spectrum disorder, and behavioral problems." (PMID 40642416, 2025). "Duplications on 17p13.3 affecting YWHAE, CRK, and/or PAFAH1B1 have been identified as susceptibility factors for intellectual disability, hypotonia, autism spectrum disorders, behavioral disturbances, brain malformations, dysmorphic facial features, and limb anomalies." (PMID 40642416, 2025). "It has been reported that a 17p deletion distal to Pafah1b1 has a distinctive phenotype: mild intellectual disability, moderate to severe growth restriction, white matter abnormalities, and developmental defects." (PMID 33083107, 2020). "Smaller microdeletions involving YWHAE but distal to PAFAH1B1 have been reported by other authors, disclosing distinct phenotypes of mild intellectual disability, moderate to severe growth restriction, white matter abnormalities, and developmental defects in brain and eye." (PMID 30208644, 2018).
autism (7 papers, 2008 to 2023). Persistent deficits in social interaction and communication and interaction as well as a markedly restricted repertoire of activity and interest as well as repetitive patterns of behavior. "We have identified a family segregating a 17p13.3 duplication extending 329.5 kilobases by FISH and array-CGH involving the YWHAE gene, but not PAFAH1B1, affected by a mild dysmorphic phenotype with associated autism and mental retardation." (PMID 23035971, 2012).
subcortical band heterotopia (7 papers, 2019 to 2025). A developmental brain abnormality characterized by atypical migration of neurons during cortical development. "Both these genes are associated with Lissencephaly 1 and Subcortical Laminar Heterotopia, with autosomal dominant inheritance for PAFAH1B1 (OMIM#607432), and with X-Linked inheritance for DCX (MIM#300067)." (PMID 38790177, 2024).
cortical dysplasia (5 papers, 2014 to 2024). "Targeted sequencing of multigene panels in next-generation sequencing for genes associated with cortical dysplasia highlighted the presence of the c.151A>G(p.(Met51Val)) variant in the DCX gene (MIM*300121) and c.1186G>A(p.(Val396Ile)) in the PAFAH1B1 gene (MIM*601545), both paternally inherited." (PMID 38790177, 2024).
lung carcinoma (5 papers, 2012 to 2024). "A previous study has shown that overexpression of PAFAH1B1 is associated with poor prognosis of lung adenocarcinoma, and the underlying mechanism may be to promote the migration and invasion of lung cancer cells by disrupting the microtubule network." (PMID 38466053, 2024). "Overexpression of PAFAH1B1 mRNA was found in 59.1% of early-stage and 78.3% of late-stage lung cancer patients of Asian descent, suggesting that the alteration of PAFAH1B1 gene may be involved in both tumor initiation and progression." (PMID 22691236, 2012). "In addition, PAFAH1B1 DNA copy number and mRNA expression level in tumor tissues was significantly higher than that of the matched-normal tissues in both Asian and Caucasian lung cancer patients." (PMID 22691236, 2012). "Only two candidate genes, PAFAH1B1 and ZNF322A, were analyzed in tumor and corresponding normal lung tissues from 24 Caucasian lung cancer patients due to the mRNA inavailability." (PMID 22691236, 2012). "The mean gene dosage of lung cancer candidate genes ARHGAP19, FRAT2, PAFAH1B1, and ZNF322A in tumor tissues was significantly higher than the corresponding normal tissues in Asian lung cancer." (PMID 22691236, 2012).
hepatocellular carcinoma (4 papers, 2014 to 2022). A malignant tumor that arises from hepatocytes. "We previously reported that the levels of Lissencephaly 1 (LIS1, also known as PAFAH1B1) are down-regulated in human hepatocellular carcinoma." (PMID 29475944, 2018).
breast carcinoma (3 papers, 2019 to 2025). "Notably, when accounting for expression of ER (ESR1), HER2 (ERBB2), and Ki-67 (MKI67), PAFAH1B1 remained associated with worse survival from breast cancer." (PMID 40378956, 2025). "To further explore the association of PAFAH1B1 with aggressive disease, we interrogated TCGA patient data and found that stratifying breast cancer patients into quartiles by PAFAH1B1 expression revealed a strong association between higher expression and worse overall survival." (PMID 40378956, 2025). "PAFAH1B1 regulates mitotic spindle orientation, proliferation, and cell migration during neurodevelopment, yet little is known regarding its function in breast cancer." (PMID 40378956, 2025). "Comparing the dependency rankings for common binding partners of dynein revealed that breast cancer cell lines were consistently far more highly dependent on PAFAH1B1 than any other dynein regulator." (PMID 40378956, 2025). "Interrogation of publicly available CRISPR essentiality screens for genes that are regulators of neural development and mitosis in breast cancer cell lines revealed PAFAH1B1 as a candidate driver of breast cancer." (PMID 40378956, 2025). "According to the Cancer Cell Line Encyclopedia (CCLE), TNBC cell lines (subclassified as Basal A and Basal B) tend to have higher expression of PAFAH1B1 than luminal breast cancer lines." (PMID 40378956, 2025). "Thus, our understanding of the function and importance of LIS1/PAFAH1B1 in breast cancer, particularly during mitosis, is limited." (PMID 40378956, 2025). "PAFAH1B1/LIS1 is a well-established modulator of dynein function; thus, we determined whether there may be a generalized impact of dynein regulators on breast cancer cell growth." (PMID 40378956, 2025). "Thus, the association of elevated PAFAH1B1 in breast cancers with worse patient outcome is not simply dependent on an elevated rate of proliferation within tumors." (PMID 40378956, 2025). "To discern the role of PAFAH1B1/LIS1 in breast cancer, we focused on TNBC to minimize confounding by different breast cancer subtypes that are driven by distinct signaling pathways." (PMID 40378956, 2025). "When considering breast cancer subtype, TNBC cell lines displayed the highest level of dependence on PAFAH1B1, with the group of luminal cell lines being modestly less dependent." (PMID 40378956, 2025). "In contrast, the impact of PAFAH1B1 on breast cancer cell growth, viability, or therapeutic response has not been explored." (PMID 40378956, 2025).
acute myeloid leukemia (2 papers, 2019 to 2022). Acute myeloid leukemia (AML) is a group of neoplasms arising from precursor cells committed to the myeloid cell-line differentiation. "This could be relevant in humans since genetic variants on Pafah1b1 have been associated with a higher risk of developing acute myeloid leukemia." (PMID 36519536, 2022).
Anxiety (2 papers, 2016 to 2020). Intense feelings of nervousness, tension, or panic often arise in response to interpersonal stresses. "We evaluated measures of anxiety-like behavior in Pafah1b1 mutant mice using measures of activity in a novel environment, defecation in the open field, percent time in the center of an open field and amount of time in the dark in a light-dark box." (PMID 26834590, 2016). "Our patient with PNES and deletion of PAFAH1B1 had normal neurodevelopment, an onset of PNES at 30 years of age, a history of anxiety and post-traumatic stress disorder (PTSD), and no history of febrile seizures or family history of seizures." (PMID 32938993, 2020).
Rett syndrome (2 papers, 2014 to 2019). A severe neurodevelopmental disorder affecting the central nervous system.
alcohol-use disorder (1 paper, 2016). "Pafah1b1 has been shown to be co-expressed with GABA type-A receptor subunits (specifically Gabra1, Gabrb2, and Gabrg2), a family of neurochemical receptors associated with alcohol-use disorder." (PMID 26834590, 2016). "This integrative genomics analysis of diverse experimental data revealed a potential novel role for Pafah1b1, a gene that had not been previously associated with alcohol-use disorder." (PMID 26834590, 2016). "A single gene, Pafah1b1, was determined to be the most highly connected and was not yet previously associated with alcohol use disorder in the annotated resources." (PMID 26834590, 2016).
Ataxia (1 paper, 2016). Ataxia refers to impaired coordination of voluntary muscle movement. "Both control and Pafah1b1 mutant animals exhibited alcohol-induced ataxia on the rotarod at 1.25 g/kg EtOH." (PMID 26834590, 2016).
bladder cancer (1 paper, 2024). "In conclusion, our analysis confirmed that the ceRNA network YARS1‐hsa‐miR‐148b‐3p/hsa‐miR‐191‐5p‐NFIA/EFEMP1/TRAK2/PAFAH1B1 is associated with bladder cancer prognosis." (PMID 38506098, 2024).
chronic thromboembolic pulmonary hypertension (1 paper, 2020). Chronic thromboembolic pulmonary hypertension (CTEPH) is characterized by the persistence of thromboemboli in the form of organized tissue obstructing the pulmonary arteries. "In vascular samples from patients with chronic thromboembolic pulmonary hypertension, Pafah1b1 expression is upregulated." (PMID 33083107, 2020).
COVID-19 (1 paper, 2023). A disease caused by infection with severe acute respiratory syndrome coronavirus 2. "We showed a significant increase in the gene expression of PAFAH1B1 in the COVID-19 GCs group, but there was no change in the expression of PAFAH1B2 and PAFAH1B3." (PMID 36851787, 2023).
Hyperglycemia (1 paper, 2013). An increased concentration of glucose in the blood. "Subsequently, the percentages of neuronal and glial cells were estimated since hyperglycemia increased the expression of Dcx and Pafah1b1." (PMID 23776576, 2013). "In order to understand the role of hyperglycemia on fate specification of NSCs, we have analyzed expression of two genes (Dcx and Pafah1b1) involved in neurogenesis and neuronal migration." (PMID 23776576, 2013).